BRAF (B-Raf proto-oncogene, serine/threonine kinase)
Diseases named in the same sentence as BRAF in open-access papers (continued):
Sharing a sentence is not in itself a finding about the gene and the disease.
thyroid nodule (continued). "In this study, we performed the molecular analysis using a new simplified procedure that involves a panel of BRAF, RAS, RET and RET/PTC gene mutations in easily obtainable FNA samples, in the attempt to improve the efficacy of the FNA diagnosis of thyroid nodules and thus patient management." (PMID 28537891, 2017). "False-negative rate of BRAF mutation testing with FNAC for thyroid nodules is increased in cases of old age, indeterminate FNAC pathology results, and certain PTC subtypes." (PMID 29132392, 2017). "We previously proposed a management guideline based on the BRAF V600E mutation status and found that performing BRAF V600E mutational analysis on FNA specimens was of great help to make a therapeutic decision of thyroid nodules when the FNA interpretation was AUS/FLU." (PMID 25648502, 2015). "While some studies suggest that the BRAF V600E mutation correlates with a high-risk phenotype in papillary thyroid microcarcinoma (PTMC), more evidence is necessary before this mutation can be used to help guide decision making in the management of small thyroid nodules." (PMID 34742355, 2021). "Although BRAF (V600E) ctDNA is detected in plasma, the corresponding index thyroid nodule FFPE sample is negative for the mutation as the sample may have been obtained from a nodule or portion of a cancer focus that did not harbor the mutation." (PMID 34475951, 2021). "Therefore, algorithmic approach of BRAF mutation analysis followed by RAS mutation and RET/PTC1 rearrangement may be of more practical help to refine FNA diagnosis of indeterminate thyroid nodules." (PMID 28417935, 2017). "Considering that 88% of the PTCs harbor either a BRAF or a RAS mutation (Thyroid, 2017, Epub ahead of time), we hypothesized that detection of RET/PTC rearrangements on BRAF and RAS mutation wild-type FNA specimens of the indeterminate thyroid nodules will improve the diagnostic yield of PTC." (PMID 28417935, 2017). "However, the false-negative rate of BRAF mutation testing with FNAC for thyroid nodules is increased in cases of old age, indeterminate FNAC pathology results, and certain PTC subtypes." (PMID 29132392, 2017). "Furthermore, preoperative BRAF mutation analysis combined with US and FNAB findings could increase the diagnostic accuracy of PTC in indeterminate thyroid nodules." (PMID 26020381, 2015). "Although the overall probabilities of PTC for thyroid nodules with MN US and FNAB findings were almost 100% (HR US, 98.7%; SM FNAB, 99.0%; MN FNAB, 99.2%, respectively), the probabilities of PTC according to each diagnostic parameter for US and FNAB were different according to BRAF mutation status." (PMID 26020381, 2015). "Recent large prospective studies have emphasized the ability of genetic markers (BRAF, RAS, RET/PTC, and PAX8/PPARγ) and protein markers (galectin-3) to significantly improve and affect the preoperative diagnostic accuracy especially for patients who have indeterminate thyroid nodules." (PMID 23326756, 2012). "As a new diagnostic method, genetic testing using molecular markers (such as BRAF, RAS, and RET) is recommended for the auxiliary diagnosis of patients with thyroid nodules when cytological results are uncertain." (PMID 36070149, 2023). "Furthermore, molecular analysis using the following markers (BRAF V600E, NRAS, HRAS, KRAS, RET/PTC, and PAX8/PPARg) to evaluate preoperative genetic mutations and rearrangements has been shown to have significant diagnostic value in thyroid nodules with indeterminate cytology." (PMID 37732121, 2023). "Analysis of more than 100,000 FNA samples, including both benign and malignant thyroid nodules, identified 895 instances of NTRK, RET, ALK and BRAF fusions, representing potentially actionable kinase fusions." (PMID 36675685, 2022). "A total of 277 consecutive patients with thyroid nodules were subjected to FNA cytology and BRAF V600E testing with ARMS‐PCR." (PMID 32671901, 2020).
thyroid nodule (continued). "The presence of RET/TPC1 rearrangement in a significant proportion (38.2%) of the patients with BRAF and RAS wild-type PTCs can be used to diagnose and manage patients with BRAF and RAS wild-type indeterminate thyroid nodules." (PMID 28417935, 2017). "Preoperative RET/PTC1 rearrangement analysis in BRAF and RAS wild-type indeterminate thyroid nodules would permit the formulation of an unambiguous surgical plan." (PMID 28417935, 2017). "In thyroid nodules with ND/UNS FNAB and IR US, the probability of PTC for BRAF-negative nodules was higher than for BRAF-positive nodules." (PMID 26020381, 2015). "The latest guidelines also suggest (recommendation rating: C) the use of molecular markers (e.g., BRAF, RAS, RET/PTC, and PAX8-PPAR) in the management of thyroid nodules with indeterminate cytology." (PMID 26693224, 2015). "Other features such as gender, multifocality, thyroiditis, presence of thyroid nodules, and mutation status of KRAS, BRAF, and TERT did not significantly differ between the high- and low-risk groups in this validation set." (PMID 40650680, 2025). "Preoperative RET/PTC1 rearrangement analysis in BRAF and RAS wild-type indeterminate thyroid nodules would permit the formulation of an unambiguous surgical plan, while foregoing the need for other less-specific diagnostic tests like repeat FNA and intraoperative frozen section evaluation." (PMID 28417935, 2017). "In particular, thyroid nodules with IR US and AUS/FLUS FNAB exhibited a significantly different probability of PTC according to BRAF mutation status (negative, 29.2% vs positive, 87.5%; P < 0.001)." (PMID 26020381, 2015). "In contrast, thyroid nodules with MN findings in US and FNAB showed almost 100% probabilities for PTC regardless of BRAF mutation status." (PMID 26020381, 2015). "Based on our prediction table, the probabilities of PTC for BRAF-positive thyroid nodules were higher than BRAF-negative thyroid nodules, except for thyroid nodules with ND/UNS FNAB and IR US." (PMID 26020381, 2015). "In view of the large number of palpable thyroid nodules that require evaluation by FNA, a search for molecular markers such as BRAF may have clinical utility." (PMID 16606457, 2006). "In addition, the BRAF 1799T>A substitution is not frequently found in thyroid nodules with indeterminate FNAB cytology." (PMID 29808165, 2018). "In total, three molecular subtypes of thyroid nodules were identified in this study: 1) CNV+, 2) CNV– and BRAF positive (BRAF+), and 3) CNV– and BRAF negative (BRAF–)." (PMID 36313748, 2022).
skin cancer (95 papers, 2009 to 2026). "Limited data exist regarding the risk of skin cancer in patients experiencing BRAF inhibitor-induced cutaneous adverse events." (PMID 39479087, 2024). "As expected, COSMIC signature 7, predominantly found in UV exposure-linked skin cancers, predicted dependency on module #20 (BRAF/MAPK1/MITF/SOX10) for cell survival." (PMID 37460547, 2023). "For example, MITF dependency has stronger association with skin cancer (SuperDendrix weight = −0.69) than with BRAF(A) (SuperDendrix weight = −0.37)." (PMID 35382456, 2022). "Selective BRAF inhibitors are associated with rapid adaptation and drug resistance as well as cause a high occurrence of secondary skin carcinoma." (PMID 35936102, 2022). "The BRAF V600E mutation is also occasionally caused by a CA>TT (i.e., TG>AA) tandem substitution, which, although infrequent, is highly enriched in skin cancers (~130-fold)." (PMID 33207206, 2020). "DrugSniper predicted BRAF vulnerability when BRAF was mutated in skin cancer (p-value = 2.59 × 10−3)." (PMID 32645997, 2020). "Our analysis indicates that the BRAF V600R and V600K mutations occur almost exclusively in skin cancers, consistent with their UV origin." (PMID 33207206, 2020). "For example, BRAF V600K mutations occur almost exclusively in skin cancers, displaying a nearly 2,000-fold greater likelihood of being observed in UV-exposed tissue as compared with other tumor types." (PMID 33207206, 2020). "By contrast, a relatively less frequently mutated gene, BRAF (46th in the list), was altered in about half of skin cancers (sample coverage 43.1%), corroborating the initial screening conducted a decade ago32." (PMID 26212640, 2015). "The initial hypothesis suggests that BRAF inhibitors impede the MAPKP, particularly pERK, inducing cell cycle arrest and apoptosis and hindering tumor advancement in BRAF-mutated skin cancers." (PMID 38893081, 2024). "Infection with certain human papillomaviruses may play a role in BRAF-inhibitor-associated skin tumor development." (PMID 39335105, 2024). "Despite major advances in the treatment of metastatic melanoma, including targeted therapy with BRAF inhibitors or immune checkpoint blockade, malignant melanoma remains the skin tumor responsible for the highest number of skin tumor-associated deaths worldwide, with approximately 55,500 cases." (PMID 35565371, 2022). "Similarly, the BRAF V600R mutation is highly enriched in skin cancers and is caused by an AC>CT (or GT>AG) tandem substitution." (PMID 33207206, 2020). "Targeting the constitutively active BRAF V600 mutant protein, in association with MEKi to prevent the paradoxical reactivation of the BRAF pathway, represents one of the most effective therapeutic strategies in the management of this potentially lethal skin cancer." (PMID 40872623, 2025). "In several clinical studies, cotargeting of BRAF together with MEK significantly delays secondary resistance, with a longer mPFS than with BRAF inhibitor monotherapy, as well as prevents formation of secondary skin tumors." (PMID 41492362, 2026). "It is essential to recognize side effects from BRAF inhibitors, such as skin rash, arthritis, or secondary skin tumors." (PMID 41031578, 2025).
skin cancer (continued). "A total of 31 patients with advanced skin cancer treated with either ICIs (n = 24) or BRAF/MEK inhibitors (n = 7) were longitudinally assessed for blood and coagulation parameters before as well as 7, 20 and 40 days after initiation of systemic tumor therapy." (PMID 39487855, 2024). "In a retrospective study using the multicenter skin cancer registry ADOReg of the Dermatologic Cooperative Oncology Group (DeCOG), 461 patients received first‐line BRAF or BRAF/MEK inhibitors, and 37 patients subsequently achieved CR." (PMID 38358050, 2024). "This prospective clinical study provides evidence that ICI or BRAF/MEKi therapy induce a pro-coagulant state in skin cancer patients." (PMID 39487855, 2024). "Outgrowth of skin tumors in cancer patients who receive therapies with BRAF inhibitors is frequently observed as an undesired side effect." (PMID 39335105, 2024). "Systemic BRAF inhibition in combination with UVB light induced skin tumors in 62% of the MmuPV1-infected animals." (PMID 39335105, 2024). "The combination of a BRAF V600E inhibitor plus a downstream MEK inhibitor avoids paradoxical activation of the MAPK pathway in normal tissues, reducing the risk of skin tumors while enhancing pathway inhibition within BRAF mutant tumors." (PMID 39392364, 2024). "Keywords in CSCC field were divided into 7 clusters: cutaneous squamous cell carcinoma, sentinel lymph node biopsy, skin cancer, B-Raf Proto-Oncogene, Serine/Threonine Kinase (BRAF) inhibitor and human Papillomaviruses, and P63 expression." (PMID 37114133, 2023). "Keywords in the CSCC domain can be divided into 7 clusters: Cutaneous squamous cell carcinoma, Sentinel lymph node biopsy, skin cancer, BRAF inhibitor, human papillomaviruses and human Papillomaviruses and P63 expression." (PMID 37114133, 2023). "The skin tumor lines with the mutant BRAF (Supertarget) were most sensitive to deletions of this gene." (PMID 37297004, 2023). "Approximately 20% of patients treated with BRAF-inhibitor monotherapy will develop secondary skin tumors and other hyperproliferative lesions, such as squamous cell carcinoma (SCC) and keratoacanthomas (KA)." (PMID 37925388, 2023). "The widely known treatment for stage IV metastatic melanoma is BRAF (B type rapidly accelerated fibrosarcoma kinase) inhibitors and with this monotherapy, NMSCs are the most commonly observed skin tumors." (PMID 35955666, 2022). "The addition of the inhibition of the downstream effector MEK improved progression-free survival (PFS) from 6.2–8.8 months to 9.9–11.4 months compared to BRAF-i alone, also reducing the secondary skin cancers rate (7% vs. 19%)." (PMID 35008245, 2021). "Limited treatment duration can decrease adverse events noted with BRAF inhibitors including skeletal pain, photosensitivity, skin tumors and renal toxicity." (PMID 34202156, 2021). "Treatment of BRAF mutant skin tumors with BRAF or MEK inhibitors vemurafenib and trametinib leads to resistance to therapy through YAP1 activation via actin cytoskeleton remodeling and RhoA-mediated inhibition of Hippo kinase LATS1." (PMID 34685695, 2021). "This study was designed for the first time for the detec- tion of mutant BRAF V600E and its correlation with clinicophathologic features in a sample of Iranian patients with pathologically proved pigmented skin neoplasms." (PMID 31531096, 2019). "We conducted this study in order to elucidate the frequency and pattern of the immunohistochemical expression of BRAF V600E among common pigmented skin neoplasms in a sample of Iranian patients living in the north of the country." (PMID 31531096, 2019).
skin cancer (continued). "A previous study revealed that tumor multiplicity and incidence of skin tumors in DT-induced two-stage skin carcinogenesis accelerated by BRAF inhibitor was decreased when a COX-2 inhibitor celecoxib was orally administrated." (PMID 31242703, 2019). "This combination therapy has demonstrated an increase in median PFS and OS, along with a decrease in the incidence of BRAF-inhibited induced skin tumors." (PMID 28052762, 2017). "This shows that BRAF inhibitors, particularly when combined with UVB light, support skin tumor growth in mice and may represent a novel way by which BRAF inhibitors contribute to skin cancer development." (PMID 39335105, 2024). "Drug-class toxicities of BRAF inhibitors encompass pyrexia, arthralgia, fatigue, headache, cutaneous toxicities and growth of secondary skin neoplasms like cutaneous squamous-cell carcinoma palmoplantar erythrodysesthesia gastrointestinal side effects and elevated serum transaminases." (PMID 36686797, 2022). "However, BRAF-i were burdened by low duration of response and cutaneous toxicity with secondary tumors development (mainly skin cancers)." (PMID 35008245, 2021). "In the 5‐year follow‐up analysis of the COmbined LGX818 (encorafenib) used with MEK162 (binimetinib) in BRAF mutant Unresectable Skin cancer (COLUMBUS) trial, LVD events were noted mostly in the first 6 months (5.1%) compared to 6–12 month (3.4%), 12–18 month (3.4%) and 18–24 month period (1.7%)." (PMID 33982883, 2021). "In the 4th edition of the 2018 WHO classification of skin tumors, lesions in the spitzoid pathway (pathway 4) are characterized by mutations in HRAS, tyrosine kinase fusions (ALK, ROS1, RET, NTRK1/3, and MET), or serine-threonine kinase fusions (BRAF, MAP3K8)." (PMID 33040161, 2021). "Although the remaining BRAF V600 variants are non-UV signature mutations, many of these are highly enriched in skin cancers." (PMID 33207206, 2020). "We obtained the mutation status of the BRAF gene in 304,517 samples available from the Catalog of Somatic Mutations in Cancer (COSMIC) database and accessed the odds ratio for specific mutations to occur in skin cancers as compared with other cancer types." (PMID 33207206, 2020). "Among non-V600 variants, the BRAF L597S, which is due to a non-UV signature CT>TC tandem substitution, is also highly enriched in skin cancers." (PMID 33207206, 2020). "A great relation between BRAF (V600E) expression and the histologic type of skin cancer was noted." (PMID 31531096, 2019). "This paradoxical stimulation is believed to be mediated by the BRAFi-induced dimerization of mutated BRAF and wild-type (WT) RAF isoforms, which enhances cellular responses such as cell proliferation, survival and growth, subsequently driving the progression of skin cancers." (PMID 39335105, 2024). "Notably, many toxicities as well as cutaneous toxicities, growth of secondary skin neoplasms or papulopustular rash may be significantly decreased and/or better tolerated in anti-BRAF/MEK combination regimens." (PMID 36686797, 2022). "In this study, we reported, for the first time, the BRAF subcellular classification in SKMs, outlining the fact that its localization (only nuclear, only cytoplasmic, or mixed expression) might serve as a prognostic indicator of this form of skin cancer." (PMID 34769348, 2021). "Furthermore, the scenario is complicated by the paradoxical development of secondary skin tumors, which may arise from the BRAF inhibitors-induced activation of MAPK pathway in wild-type BRAF cells." (PMID 28118616, 2017). "In addition, the use of BRAF inhibitors may result in the development of secondary skin cancer, further limiting the therapeutic benefit of this monotherapy." (PMID 28052762, 2017).